CD163 (CD163 molecule)
Diseases named in the same sentence as CD163 in open-access papers (continued):
Sharing a sentence is not in itself a finding about the gene and the disease.
tumor (continued). "First, coculture with tumor cells inhibited the expression of M1-related genes encoding IL-6, TNF-α, and IL-1β and increased the expression of M2-related genes encoding CD163, Arg1, IL-10, TGF-β, and VEGFA, as well as expression of TNF-α and CD163 at protein level." (PMID 34093857, 2021). "First, CD163-positive TAMs could affect the tumor-infiltrating lymphocytes (TILs) in TME." (PMID 32756500, 2020). "Furthermore, higher CD163 expression was associated with better outcome in women with no residual tumor after primary surgery (P = 0.02)." (PMID 31980961, 2020). "Recently, it was reported that tumor-associated macrophages may be the predominant source of LPA production in the ascites of ovarian cancer patients, and that CD163+CD206+ tumor-associated macrophages play an essential role as the main producers of ATX and phospholipase A2s (PLA2s)." (PMID 32824846, 2020). "Thus high infiltration of M1 macrophages (CD68+iNOS+) in tumor islets was associated with increased overall survival (OS) in NSCLC, while high infiltration of total M2 macrophages (CD68+CD163+) in tumor islets and stroma was associated with reduced OS in NSCLC." (PMID 33194645, 2020). "Interestingly, FOLR2, CD163, LILRB5, CD209 and C1QC were identified as genes of the “anti-inflammatory gene set”, whose expression is also seen in tissue-resident macrophages and tumor-associated macrophages." (PMID 32532019, 2020). "The M1 subset, which is involved in antitumor immunity and anti-angiogenesis and M2 CD163+ subset, have the opposing roles of enhancing immunosuppression and angiogenesis in tumor progression, and may be considered the two extremes of a large spectrum that can exert anti- and pro-tumoral activities." (PMID 32731512, 2020). "However, higher CD163 expression was associated with better outcome in the subgroup of patients with no macroscopic tumor after surgery in our cohort." (PMID 31980961, 2020). "However, in the subgroup of patients with no macroscopic residual tumor, higher CD163 expression was associated with better outcome (P = 0.02)." (PMID 31980961, 2020). "However, in our cohort, tumor overexpression of PD-L1 or β-catenin in association with intratumoral or peritumoral CD8+ T lymphocytes or CD163+ was not an independent prognostic factor at multivariate analysis." (PMID 31730502, 2019). "However, high CD163+ M2 infiltrates correlated with high pT-stage and large tumor diameter, suggesting that M2 macrophages may contribute to the tumor growth and progression of PDAC." (PMID 31771616, 2019). "Preoperative diagnostic biopsies (n = 26), tumor resection specimens (n = 34), tumor-free lymph nodes (n = 28) and lymph node metastases (n = 10) of T1/T2 oscc patients were immunohistochemically analyzed for Gal3 and macrophage marker (CD68, CD11c, CD163 and MRC1) expression." (PMID 30115022, 2018). "Knocking-down CD163 in cancer cells could inhibit tumor growth in vivo." (PMID 29152078, 2017). "As previously detailed, our primary cell cultures were negative for markers of hematopoietic cells (CD45), tumor-associated macrophages (CD163), activated hepatic stellate cells (GFAP), endothelial cells (CD31), fibroblast-activation protein (FAP), and stromal-derived factor (SDF1)." (PMID 28873435, 2017). "We have shown that the differential densities and spatial distribution of CD8+ and CD163+ cells as described by the FCIS could identify patients with increased DFS or patients who lived longer despite the fact that these were in late tumor stages according to the TNM classification." (PMID 28428887, 2017). "While, the expression of CD163 in cancer cells of lymph node had no significant alteration compared with its expression in primary tumor cells, suggesting CD163 in cancer cells may not be a crucial risk for lymphatic metastasis." (PMID 29152078, 2017). "The interconnected CD163+ tubules may represent vascular mimicry channels in a benign tumor." (PMID 27834402, 2016).
tumor (continued). "Also, numerous interspersed CD163+ cells (TAMs) were seen in the tumor mass." (PMID 27936099, 2016). "Furthermore, using CD163 immunohistochemistry, it has been hypothesized that tumor microenvironment in cHL as well as in solid tumors is enriched in M2 macrophages." (PMID 25978381, 2015). "In addition, the density of CD163+ TAMs correlated with tumor infiltrating lymphocytes (TILs)." (PMID 26714314, 2015). "This could explain why the decrease in CD3 (T-cells) and CD2 (T-cells, B-cells, NK cells) was more pronounced than that of CD8α (cytotoxic T-cells, NK cells, subset of DC), CD68 (macrophages, neutrophils, DC, myeloid progenitors), and CD163 (pro-tumor macrophages, M2)." (PMID 26374556, 2015). "Our present findings also strongly suggest that IL-8 expression and the infiltration of CD163-positive M2 macrophages in the tumor microenvironment might be biomarkers for affecting and for predicting the clinical outcome of patients with any stage of OSCC, including advanced OSCC (Stage III/IV)." (PMID 25461761, 2014). "Thus, IL-8 and CD163-positive macrophages might elicit tumor relapse and/or post-operative cervical LN metastasis via any other mechanisms besides tumor angiogenesis (e.g., the suppression of antitumor immunity) in the tumor microenvironment." (PMID 25461761, 2014). "In ovarian cancer, embryonic TAMs expressing CD163 and T‐cell immunoglobulin and mucin‐domain containing molecule 4 (Tim4) produce high levels of IL‐6 and erythropoietin, activating STAT3 to promote tumor progression and invasion." (PMID 41426206, 2026). "We applied multiplex immunofluorescence to pre-treatment tumor samples from 11 patients with advanced BTC, staining for CD4, CD8, CD20, and CD163 to identify T cells, B cells, and macrophages." (PMID 42293570, 2026). "The corresponding multiplex immunofluorescence results for CD163 and CD3 in RDH16-high and RDH16-low tumor regions are presented." (PMID 41601632, 2026). "Immunohistochemically, tumor cells diffusely expressed cytokeratins, vimentin, CD68, CD163, and EMA, with focal expression of SMA, S-100, calponin, and CD3, but were negative for CD21, CD35, CD1a, ALK, and HHV8." (PMID 42311660, 2026). "In addition, high BGN expression was significantly associated with tumor invasion depth (p < 0.001), lymphatic vessel invasion (p = 0.001), and increased expression of CAF markers, αSMA (p = 0.003) and FAP (p = 0.022), and macrophage markers, CD68 (p = 0.049) and CD163 (p = 0.007), in ESCC tissues." (PMID 41465449, 2025). "Similarly, a recent study of an M2-like macrophage marker showed that increasing CD163+ immune cells were also associated with pronounced improvement in overall survival in TNBC, even though this marker is generally regarded as signifying a pro-tumor microenvironment." (PMID 40593864, 2025). "First, we determined the optimal passage of primary tumour cells for co-culture by culturing from passage 0 (P0) to passage 6 (P6) and assessing immune marker expression (CD68, CD163, and TMEM119) via western blotting." (PMID 40420192, 2025). "To further investigate CTSS-mediated tumor immunity, we assessed CD4+ T-cell and M2 macrophage (CD163+ cells) infiltration in MC38 tumors." (PMID 40794185, 2025). "Serum IL-6 had a positive correlation with tumor IL-6 expression (ρ = 0.56, p < 0.0001) and an inverse correlation with the CD8/CD163-positive cell count ratio (ρ = −0.4, p < 0.01)." (PMID 39652104, 2025). "Flow cytometry demonstrated increased CD163+ M2 macrophage numbers in the liver PMN and MMN of MC38 tumor-bearing mice, contrasting with CD68+ M1 macrophages which showed no increase." (PMID 40765822, 2025). "M2 expresses high levels of CD163, CD206, CCL18, and CCL22, releasing anti-inflammatory (TGF-β, IL-4, and IL-13) and inflammatory (IL-6, IL-12, and TNF-α) factors, as well as tumor-promoting arginase-1 and VEGF, modulated by TME signals." (PMID 40940877, 2025).
tumor (continued). "More than 50% of MCs were colocalized with neighbouring cells of the tumour microenvironment within 20 μm, most frequently with monocytes (CD14+CD68+), M2 macrophages (CD68+CD163+), and endothelial cells (CD31+)." (PMID 40981193, 2025). "By identifying these subtypes through markers such as CD68 (general macrophage marker), CD163, CD204, and CD206 (M2 markers), researchers can assess the tumor microenvironment and predict patient outcomes." (PMID 40330466, 2025). "The expression of PD-L1 and the tumor microenvironment markers (CD4, CD8, CD68, and CD163) were examined in LSCC using immunohistochemistry." (PMID 40429363, 2025). "After adjusting for tumor purity, CXCL8 expression showed strong positive correlations with M2 macrophage markers (CD163, VSIG4, MS4A4A) in Gr." (PMID 41432874, 2025). "IHC results demonstrated significant expression of BCL2A1, CD68, and CD163 within the tumors, with BCL2A1 exhibiting a distribution pattern highly similar to that of CD68 and CD163, primarily localized in the tumor stroma region." (PMID 40707992, 2025). "There is a positive connection between CD163+ TAMs in the TME and PD-L1 expression in many tumor types, including pancreatic and liver tumors." (PMID 40422244, 2025). "Immunohistochemical staining of the second resection specimen showed that tumor cells were positive for CD68, CD163, CD4, INI-1 and ATRX, Scattered focal positivity for lysozyme, and some positive for S-100 and LCA." (PMID 40231251, 2025). "To investigate the main subtype of myeloid cells in the tumor boundary, we compared some classical markers of myeloid subtypes and found that MRC1 had the same expression pattern as CD163." (PMID 39670859, 2025). "Assessment of tumor immunogenicity by immunohistochemistry revealed the following number of immune cells: CD8+ cells - 15 per 1 mm2, CD68+ – 7 per 1 mm2, CD163+ macrophages – 35 per 1 mm2." (PMID 39936166, 2025). "Tumor samples were examined histologically and immunohistochemically for CD68+ and CD163+ macrophages, and quantitative analysis was performed in intratumoral and peritumoral regions." (PMID 41007741, 2025). "The results revealed a significant increase in the protein levels of CD163, CD14, and CD68 in the tumor tissue compared to adjacent tissue (p < 0.0001)." (PMID 40270962, 2025). "Our results show a higher expression of CD68 in the tumor stroma of brain metastases, whereas CD86 and CD163 showed comparable levels in both locations." (PMID 40510346, 2025). "In glioma macrophages, CCL3 is a marker of the anti-tumor fraction, while CD68 and CD163 are markers of the pro-tumor fraction." (PMID 40191211, 2025). "This study revealed progressively elevated CD163+ and CD86+ TAMs levels in colorectal tissues: normal mucosa < CRA < CRC, suggesting their potential involvement in immune modulation during tumor progression." (PMID 41395618, 2025). "To assess the impact of lidocaine on macrophage polarization within the tumor microenvironment, we evaluated the expression of CD163 and CD40 on CD14+ tumor-infiltrating immune cells (TIICs)." (PMID 40244064, 2025). "The protein levels of macrophage-related genes, including CD163, CD14, and CD68, were assessed using immunohistochemistry (IHC) on tumor tissues and adjacent tissue microarray." (PMID 40270962, 2025). "We observed that a robust TAAs expression together with a favorable immune infiltrate contexture inside the tumor (high intratumoral CD8 + cells/low FOXP3 + Treg and CD163 + myeloid cells) improve the vaccine ability to protect pts from cancer recurrence." (PMID 40251644, 2025).
tumor (continued). "High rates of CD68+CD163− (p = 0.044), CD68+CD163+, and CD68+CD206+ macrophages (p < 0.001) were significantly favorable for 10-year DFS only in the stromal compartment of tumor-distant normal tissue." (PMID 40498004, 2025). "Comparative analysis of BCL2A1+macrophages from tumor and adjacent normal tissues revealed highly similar expression of macrophage marker genes (e.g., CD68, CD163)." (PMID 40707992, 2025). "CD163+ and CD8+ cells were frequent in both tumor and stroma, while the FoxP3+ cell density was relatively low." (PMID 40422521, 2025). "This function is critical for effective DC-based immunotherapies but is often hampered by tumor-derived immunosuppressive factors, as is observed for CD14+CD163+ tumor-induced DC3s (ti-DC3s)." (PMID 40789452, 2025). "scRNA-seq data showed that BCL2A1+macrophages in tumor and normal tissues had highly similar expression of macrophage marker genes (such as CD68 and CD163), indicating consistent fundamental macrophage characteristics." (PMID 40707992, 2025). "In the present study, we found that the overall distribution of CD163+ immune cells was similar between PT, LNM and DM, although statistically insignificant shifts were observed during tumor progression." (PMID 39751847, 2025). "Over 50% of immune cells were CD68+ macrophages, predominantly CD68+HLA-DR−CD163− M0 and CD68+CD163+ M2 subtypes over the CD68+HLA-DR+ M1 subtype, suggesting a pro-tumor and immunosuppressive TME." (PMID 40940877, 2025). "While MMP-9, TNC, and POSTN support tumor progression through ECM remodeling, CD163 is involved in tumoral immune suppression." (PMID 41450913, 2025). "In vivo, MEL-dKLA treatment significantly reduced tumor growth, decreased the number of CD163+ M2 macrophages, and increased CD8+ T cell infiltration in tumor tissues." (PMID 41019043, 2025). "Assessment of tumor immunogenicity by immunohistochemistry revealed the following number of immune cells: CD8+ cells - 11 per 1 mm2, CD68+ – 6 per 1 mm2, CD163+ macrophages – 3 per 1 mm2." (PMID 39936166, 2025). "To evaluate TAM abundance across HNSCC, BC and CRC tumor samples, we developed a 4-plex mIF assay to detect CD68, CD163, PD-L1 and cytokeratin." (PMID 41415295, 2025). "CD163+ macrophages remain responsive to CD47 blockade, making them promising immunotherapy targets in OC despite tumor-induced immunosuppression." (PMID 41280929, 2025). "We also examined the relationship between GALNT7 staining and tumor cell PD-L1 positivity, Tn antigen H-score, and infiltration of CD8+ TILs, CD4+ TILs, Foxp3+ TILs, and CD163+ macrophages, stratified by MMR/MSI status." (PMID 40824763, 2025). "Comparative transcriptomic analysis of human HCC, normal liver tissue, and fetal liver revealed the presence of distinct macrophage populations in tumor tissue, initially subdivided by high (TAM1s) or low (TAM2/3 s) expression of CD163." (PMID 40721870, 2025). "IgE engagement of monocytes via the Fc region induced tumor cell cytotoxicity and a pro-inflammatory shift with upregulation of immune-stimulatory CD40, CD80 and CD86, and downregulation of scavenger CD163, cell surface molecules." (PMID 40074330, 2025). "Tumor-infiltrating CD68+ pan-macrophages, CD163+ M2 like- macrophage, and CD8+ T cells were assessed using immunohistochemistry and immunofluorescence." (PMID 41573553, 2025). "Reduced CD163+ and CD206+ TAMs; increased CD8+ T-cell infiltration; decreased tumor volume and metastasis." (PMID 40918451, 2025). "We employed immunostaining for CD3, CD4, CD8, Granzyme B (GzmB), FOXP3, CD163, and CD68 markers to quantitively analyze the STR patient’s tumor immune landscape both at baseline and during STR 10–12." (PMID 40594889, 2025). "Immune cell infiltration levels, including CD4, CD8, FOXP3, CD163‐positive cells and expression levels of TGFβ1 and SMAD3 proteins in tumor tissue were evaluated by immunohistochemistry." (PMID 41187938, 2025).
tumor (continued). "As expected, LPS/IFN-γ treatment increased HLA-DR+CD80+ (p = 0.040) expression in macrophages (anti-tumor macrophages) and M-CSF induced CD206+CD163+ (p = 0.0082) macrophages (immunosuppressive macrophages)." (PMID 40362334, 2025). "In the 4C analysis, we found that high infiltration of CD68+CD163+ macrophages correlated with improved DFS, particularly in the stromal compartment of tumor distant normal tissue." (PMID 40498004, 2025). "Immunohistochemistry showed strong positivity for CD163 and CD68, indicating a histiocytic lineage in the tumor cells." (PMID 40901224, 2025). "Using tumor‐derived PGE2 from A375 CM, the addition of aEP2 or aEP2/4 downregulated CD163, MerTK, and CD14 expression, which indicates a less suppressive macrophage phenotype." (PMID 41211769, 2025). "Among the most established biomarkers are members of the scavenger receptor family, such as CD206, CD163, stabilin-1, Marco, CD36, and CD204, which are expressed on CD68+ macrophages in tumor tissues." (PMID 41417432, 2025). "The tumor microenvironment of patients with elevated COX-2 expression is examined, revealing a significant increase in CD163+ cells." (PMID 41431078, 2025). "Functionally, COL10A1+Fib significantly promoted the migration of M0 macrophages and localized near CD163+ and CD206+ M2 macrophages (Primary Tumor: n = 35)." (PMID 40826474, 2025). "In TAMs, phlorotannins reduced the expression of M2-like markers (CD163 and CD209) and decreased the secretion of IL-10, IL-17, and VEGF, all of which collectively support tumor progression." (PMID 41590709, 2025). "While the observed correlations between FGFR2 and CD163+ or FOXP3+ immune cells are modest, their selective presence in ER+ tumours is noteworthy and warrants further investigation." (PMID 41018083, 2025). "Although it had a small sample size, our m-fIHC analysis confirmed the significant increase in CD4+ T-lymphocytes (CD3+/CD8−) in the tumor area of TIL-B-rich tumors, while CD8+ T-lymphocyte and CD163+ macrophage infiltration levels were comparable." (PMID 39796740, 2025). "Concomitantly, the expression of the M2 markers CD163 and CD11b was higher in THP-1 cells co-cultured with tumor cells." (PMID 40408281, 2025). "Integrative analysis showed that the most dominant pairwise cell-cell contacts in mFGFR2 iCCA were between tumor cells and CD11b+/CD15+ granulocytes as well as between tumor cells and αSMA+ fibroblasts and CD68+/CD163- macrophages." (PMID 39969434, 2025). "There were tumor areas where IBA1 and CD163 were strongly and widely expressed throughout the tissue." (PMID 40191733, 2025). "Namely, CD163+ cells are distributed throughout the stroma, whereas CD204+ and CD206+ cells are predominantly concentrated near the tumor nest." (PMID 40432828, 2025). "The higher levels of CD163 + immune cells (M2 macrophages) in the patients with longer survival could indicate signs of an immune-suppressed TME, as M2 macrophages are usually associated with immune suppression, increased tumor aggressiveness, early recurrence, and a poor prognosis." (PMID 40310569, 2025). "The tumor progression, including resistance of apoptosis, angiogenesis, and proliferation, is strongly influenced by higher infiltration of M2‐TAM (CD163 and 204) and upregulation of STAT3, NF‐κB pathways." (PMID 41263059, 2025). "Strikingly, macrophages co-cultured with MNAT1-knockdown tumor cells showed reduced expression of the M2 markers CD206 and CD163, indicating that MNAT1 knockdown suppresses M2 polarization of macrophages, thereby impeding tumor progression." (PMID 41235252, 2025). "In contrast, more CD163+ and CD206+ M2 macrophages were recruited and distributed continuously in the residual tumor tissue and the addition of Nano-IFNγ/Zole significantly reversed this tendency." (PMID 39776793, 2025). "Immunohistochemistry showed that the tumor cells were positive for molecules such as CD68 and CD163." (PMID 40231251, 2025).